ARL13B (ARF like GTPase 13B)
Diseases named in the same sentence as ARL13B in open-access papers (continued):
Sharing a sentence is not in itself a finding about the gene and the disease.
epilepsy (1 paper, 2021). A brain disorder characterized by episodes of abnormally increased neuronal discharge resulting in transient episodes of sensory or motor neurological dysfunction, or psychic dysfunction. "Indeed, cilia dysfunction resulting from the selective loss of ciliary GTPase Arl13b affects cilia growth and also reduces the morphological complexity of parvalbumin-positive interneurons, a subset of inhibitory neurons implicated in multiple forms of epilepsy." (PMID 34445580, 2021).
gastric cancer (1 paper, 2020). A primary or metastatic malignant neoplasm involving the stomach. "Shao and co-authors showed that ARL13B promotes proliferation, migration and invasion of gastric cancer cells both in vitro and in vivo, through activation of Smoothened (Smo) and consequent activation of Hh signaling." (PMID 32426352, 2020).
Lowe syndrome (1 paper, 2017). "Upon immunofluorescence staining with OCRL specific antibodies and anti-Arl13b (a small GTPase) antibodies, a marked decrease in OCRL signal was noted in the trabecular meshwork of the Lowe syndrome patient tissue, as compared to the normal human cadaveric control eye." (PMID 28473699, 2017).
mental disorder (1 paper, 2019). A disease that has its basis in the disruption of mental process. "Interestingly, a shortening of primary cilia by conditional Arl13b knockout re-shaped interneuronal connectivity and may underpin human mental disorders." (PMID 31850339, 2019).
polycystic kidney (1 paper, 2020). "The expression of ARL13B in foetal polycystic kidney tissues with mutated CEP290 protein was similar to the normal kidney tissues with wild‐type CEP290 protein." (PMID 31840411, 2020). "In order to observe the effect of CEP290 variant on ciliary structure, we detected the localization and expression of ARL13B (ADP‐ribosylation factor‐like protein 13B) in both normal and foetal polycystic kidney tissues by immunofluorescence assay." (PMID 31840411, 2020).
pulmonary embolism (1 paper, 2018). The obstruction of the pulmonary artery or one of its branches by an embolus, sometimes associated with infarction of the lung. "Rs193219215 on ADP ribosylation factor-like GTPase 13B (ARL13B), which interacts with Intraflagellar transport 74 (IFT74), was found in two cases with pulmonary embolism (SN3230 and SN8592)." (PMID 29368655, 2018).
retinal detachment (1 paper, 2025). An eye emergency condition which may lead to blindness if left untreated. "On day 7, retinal detachment was observed in both groups, but more severe in the ARL13B KD group, the majority of which progressed to stage 3, while scrambled controls remained at stage 2." (PMID 41425088, 2025).
tumor (13 papers, 2016 to 2024). "In our study, we examined tumor cells endogenously expressing ARL13B with overexpression of WT or mutant variants." (PMID 37830570, 2023). "GTPase Arl13b is a newly identified partner and regulator of Smo, and Arl13b expression is closely associated with tumour size and invasion depth." (PMID 29899399, 2018). "Factors that regulate SMO levels, like Arl13b, may be important in tumor progression, as upregulated SMO expression is associated with decreased overall survival of GBM patients." (PMID 30410731, 2018). "Inhibition of ARL13B with shRNA or ciliogenesis using ciliobrevin slowed tumor growth and reduced stem cell markers and SHH pathway activation." (PMID 37830570, 2023). "Recent studies suggest ARL13B is critical for tumor growth in vitro and in vivo, as well as for angiogenesis within GBM." (PMID 37830570, 2023). "We next asked if either of the treatment paradigms that slowed tumor cell recurrence correlated with the presence of ARL13B+ cilia." (PMID 35359402, 2022). "Surprisingly, the inhibitory effects of TTFields and TMZ on tumor cell recurrence are linked to the relative timing of TMZ exposure to TTFields and ARL13B+ cilia." (PMID 35359402, 2022). "Both in TCGA and Oncomine databases, ARL4C and ARL13B were significantly up‐regulated in tumour tissues." (PMID 33724652, 2021). "We also costained luminal and claudin-low tumor sections for vimentin, E-cadherin, Arl13b, and γTubulin to assess EMT status and primary cilia representation." (PMID 34705506, 2021). "ARL13B was also involved in the GBM development, and the protein level of ARL13B was higher in tumor samples than in normal samples." (PMID 32874133, 2020). "Tagging GBM primary cilia with Arl13b:GFP allowed us to observe other behaviors and characteristics of those cilia and associated tumor cells." (PMID 30410731, 2018). "In addition, multiple studies have found that disrupting key ciliary regulators such as KIF3A and ARL13B on GBM cells derived from various subtypes somewhat consistently prolonged survival in tumor-bearing mice." (PMID 38630257, 2023). "First, the combined effects of TMZ and TTFields may depend on the degree of ARL13B+ cilia in the tumor." (PMID 35359402, 2022). "Moreover, our results revealed a new mechanism to explain the role of ARL13B in tumor progression, through the modulation of cell-ECM adhesion and integrin-mediated signaling." (PMID 32426352, 2020). "Inhibiting expression of KIF3a, PCM1, ARL13B, or IFT88, all proteins required for ciliogenesis, can sensitize patient-derived tumor cells to TMZ in vitro and in vivo." (PMID 38630257, 2023). "Remarkably, staining with the cilia markers ARL13B and γ-tubulin revealed GFP+ multiciliated tumor cells within 72 h of treatment." (PMID 35322202, 2022). "Finally, we explored whether TTFields affects ARL13B+ cilia in the patient tumor microenvironment." (PMID 35359402, 2022). "A recent study found that Arl13b directly binds to and stabilizes SMO and that higher levels of Arl13b prevent the degradation of SMO and accelerate tumor growth." (PMID 30410731, 2018). "Then these tumor samples and adjacent normal tissues underwent immunohistochemistry (IHC) staining with antibody for VHL and immunofluorescence (IF) staining with cilia marker Arl13b." (PMID 39389955, 2024). "Knockdown of ARL13B/cilia using shRNA in patient-derived xenografts in vivo not only slowed tumor growth but increased sensitivity to TMZ in vivo." (PMID 35359402, 2022). "Although Arl13b is implicated in tumor growth, our data suggest that Arl13b released from GBM cilia does not mediate tumor cell proliferation." (PMID 30410731, 2018). "However, TMZ before or after TTFields application slowed tumor cell recurrence, an effect not observed in ARL13B-depleted cells." (PMID 35359402, 2022).
cancer (6 papers, 2013 to 2020). A tumor composed of atypical neoplastic, often pleomorphic cells that invade other tissues. "However, the loss of Arl13b has also been shown to lead to increased SMO levels in the primary cilia of non-cancer cells, to ultrastructural defects in the cilium, and to aberrant polarity and proliferation of neural stem cells in the developing brain." (PMID 30410731, 2018). "We also labeled tumorspheres for Sox2 (a marker for cancer stem cells), Arl13b, and pericentrin to determine if cilia are present on cancer stem cells." (PMID 32811879, 2020). "Furthermore, immunohistochemical analysis shows that Arl13b expression is detected mainly in ductal epithelial cells of normal adjacent breast tissues (black arrows), whereas carcinoma cells are strongly stained for Arl13b (arrowheads)." (PMID 31569511, 2019). "Ac-Tub and Arl13b were observed to co-localize in cilia found on normal and cancer tissues." (PMID 24987519, 2014). "Ac-Tub and Arl13b always colocalized in cilia of normal and cancerous prostate, demonstrating that lack of detection of cilia in cancer is due to loss of cilia and not loss of acetylation of tubulin." (PMID 23844214, 2013). "Therefore, we hypothesized that Arl13b regulates migration and invasion of cancer cells through actin cytoskeleton-related mechanisms." (PMID 31569511, 2019). "Therefore, the mechanisms governing Arl13b-induced tumorigenesis and cancer progression might differ between different cancer types." (PMID 31569511, 2019). "Thus, future studies should investigate the contribution of Arl13b-regulated actin remodeling and FA dynamics, as well as canonical and non-canonical Shh signaling for tumorigenesis and cancer progression." (PMID 31569511, 2019). "However, the molecular mechanism by which Arl13b regulates cancer cell migration and invasion is not understood." (PMID 31569511, 2019).
neurodevelopmental disorder (2 papers, 2021 to 2022). A behavioral and cognitive disorder with onset during the developmental period that involves impaired or aberrant development of intellectual, motor, or social functions. "Selective loss of ciliary ARL13B in interneurons has been shown to alter their morphology and synaptic connectivity, leading to the disturbance of the excitatory/inhibitory excitatory balance, which is one of the mechanisms underlying neurodevelopmental disorders such as ASD." (PMID 34448047, 2021). "Consistent with this, pathogenic variants in EXOC2 cause a severe neurodevelopmental disorder with dysmorphic facies and cerebellar hypoplasia (MIM# 619306) leading to reduced exocytosis and defective Arl13B localization to the primary cilia in patient cells." (PMID 36150098, 2022).
animal diseases (1 paper, 2018). "Since D/D-mediated Arl13b targeting is not found in other eukaryotes except for the kinetoplastids, this docking machinery presents an attractive therapeutic target for a range of human and animal diseases caused by this group of parasites." (PMID 30097558, 2018).
infection (1 paper, 2025). The state of being infected such as from the introduction of a foreign agent such as serum, vaccine, antigenic substance or organism. "Within the hPIV-3-infected PCLS, infected ciliated epithelial cells could be observed with partial co-localization of HPIV3-HN antigen and Cilia arl13B, indicating an active infection with hPIV-3 in these cells." (PMID 41239423, 2025).
ARL13B also shares sentences with these, for which no sentence is quoted: Joubert syndrome 8 (2 papers); adrenocortical carcinoma (1); alkaptonuria (1); Asperger syndrome (1); autism spectrum disorder (1); autistic disorders (1); Bardet-Biedl syndrome (1); basal cell carcinoma (1); Carpenter syndrome (1); cervical cancer (1); cognitive delay (1); colon cancer (1); cystic kidneys (1); deafness, autosomal recessive 1A (1); Hydrocephalus (1); Hyponatremia (1); Joubert syndrome 1 (1); myopathy (1); Obesity (1); Osmotic Demyelination Syndrome (1); proliferative vitreoretinopathy (1); renal fibrosis (1); retinal ciliopathy (1); retinal diseases (1); Retinal dystrophy (1); Rod-cone dystrophy (1); silicosis (1); Usher syndrome (1).